PATE3 (prostate and testis expressed 3)
Synonyms: PATE-DJ; HEL-127
Tractability: Antibody: UniProt places it where antibodies can reach, with high confidence; UniProt predicts a signal peptide or a membrane-spanning region; its Gene Ontology location is reachable by antibodies, with medium confidence.
Gene: Protein-coding gene on chromosome 11 (125,788,127 to 125,791,600, forward strand). Ensembl gene ENSG00000236027.
Subcellular location: Secreted
Gene Ontology:
Cellular component: extracellular region
Genetic constraint (gnomAD): Loss-of-function variants: 5 observed, 5.81 expected, observed/expected ratio (o/e) 0.86, 90% interval 0.45 to 1.69. That is too few expected variants to judge how well the gene tolerates losing a copy. Missense variants: 77 observed, 85.26 expected, observed/expected ratio (o/e) 0.9, 90% interval 0.75 to 1.09. Synonymous variants: 26 observed, 29.34 expected, observed/expected ratio (o/e) 0.89, 90% interval 0.65 to 1.23.
Homologues: Orthologues: chimpanzee PATE3 (98% identical), macaque PATE3 (87% identical), dog PATE3 (73% identical), pig PATE3 (71% identical), rabbit PATE3 (70% identical), mouse Pate3 (64% identical), rat Pate3 (63% identical), guinea pig PATE3 (51% identical). Paralogues in human: PATE1 (37% identical), ACRV1 (30% identical), PATE4 (23% identical), PATE2 (22% identical).